DRD2 (dopamine receptor D2)
Diseases named in the same sentence as DRD2 in open-access papers (continued):
Sharing a sentence is not in itself a finding about the gene and the disease.
tumor (continued). "However, these tumor suppressive effects may be attenuated by epigenetic modifications, such as tumor-suppression genes ZDHHC1 and DRD2." (PMID 34805183, 2021). "In PitNETs expressing DRD2, modulation of P-FLNA might suggest new pharmacological strategies to overcome drug resistance and P-FLNA might represent a new molecular biomarker for tumor responsiveness to DAs." (PMID 33664708, 2020). "In addition, DRD2 knockout in ARK2 cells did not completely abrogate the tumor-suppressor effect of ONC206, suggesting that other D2-like receptors independent pathways may play a role in modulating the effect of ONC206 in USC cells." (PMID 32867127, 2020). "Therefore, we screened a large tumour set for receptor mRNA overexpression using functional genomic mRNA (FGmRNA) profiling, and we analysed protein expression and location of 5-HTR1B, 5-HTR2B, DRD1, and DRD2 with immunohistochemistry in different tumour types." (PMID 31478179, 2020). "Dopamine receptor type 2 (DRD2) mediates a reduction of p-AKT in a subgroup of non-functioning PitNETs (NF-PitNETs) and in prolactin-secreting tumor cells (MMQ cells) through a β-arrestin 2-dependent mechanism." (PMID 35721701, 2022). "Although DRD2 knockout does not abrogate the anti-cancer effect of imipridones, enhanced DRD2/DRD5 heterodimerization was inversely correlated with tumor cell sensitivity to ONC201." (PMID 33922062, 2021). "We have also profiled expression of DRD2, 3, and 4 mRNA in GBM patient samples, and non-tumor samples." (PMID 33945569, 2021). "In the present study, DRD2 knockout mice were selected as the model, and inhibition of MAPK14 reduced the secretion of PRL and growth of tumor, suggesting that DRD2 activation is not the only means of regulation of expression of PRL." (PMID 32894113, 2020). "However, in gonadotropin-storing tumors we observed a negative correlation between DRD2 expression and tumor size (r = −0.36, p = 0.03), while in null cell adenomas, a positive correlation was found between DRD5 mRNA expression and tumor size (r = 0.66, p = 0.004)." (PMID 32971845, 2020).
psychiatric disorder (92 papers, 2003 to 2025). A disorder characterized by behavioral and/or psychological abnormalities, often accompanied by physical symptoms. "Several published articles have identified the A1 allele of the DRD2 Taq1A polymorphism as a potential risk factor for various psychiatric disorders." (PMID 40727586, 2025). "The correlation of DRD2 Taq1A polymorphism with several associated psychiatric disorders has been a research hotspot." (PMID 40727586, 2025). "Study of DRD2 Taq1A polymorphism in Indian population provides insight into differential susceptibility to psychiatric disorders, and possible pharmacogenetic responses." (PMID 40727586, 2025). "Other genetic studies have identified over 4000 variants in DRD2, some of which were shown to be related to risk for psychiatric disorders in genome-wide association studies (GWAS)." (PMID 28673279, 2017). "DRD2 rs1800497 polymorphism is associated with various psychiatric diseases." (PMID 32764574, 2020). "Many studies have concentrated on determining whether variants in DRD2 confer susceptibility to addictive disorders including smoking-related phenotypes and other psychiatric disorders." (PMID 26624925, 2015). "This may provide biological explanations why genetic variants on several psychiatric disorder-associated genes such as DRD2 and COMT have been selected or maintained through evolution in humans." (PMID 26136653, 2015). "In humans, the DRD2 gene on Chr 11q23.2, which encodes the dopamine D2 receptor, harbors several genetic variants previously linked to variability of D2 receptor expression as well as individual differences in motivated behavior and risk for psychiatric disorders." (PMID 28507526, 2017). "This evidence indicates that DRD2 antagonists can ameliorate adverse symptoms in response to psychological stimuli, further suggesting a role for DRD2 in the prodromal symptoms of psychiatric disorders." (PMID 40226707, 2024). "CPZ is a well-known DRD2 antagonist and therefore has been successfully used in the treatment of psychiatric disorders." (PMID 38162492, 2023). "Abnormal DRD2 expression and dopamine signaling dysfunction in several mental disorders have become critical therapeutic targets of antipsychotic drugs." (PMID 37274216, 2023). "Although the Taq1A SNP (rs1800497) is the most commonly studied genetic variation in different psychiatric disorders, more variations in the DRD2 gene should be examined to obtain a comprehensive assessment of genetic information." (PMID 34086098, 2022). "CPZ is the progenitor of the DRD2 inhibitors phenothiazines and is used since the 50s in the therapy of several psychiatric disorders, e.g. acute and chronic psychosis, and provides relief from severe vomiting and untreatable hiccups." (PMID 33718225, 2021). "The presence in serum of IgG autoantibodies against 5-HT1A (anti-5-HT1A) and dopamine receptor D2 (anti-D2R) in psychiatric disorders was studied by radioimmunoassay (RIA)." (PMID 28725222, 2017). "This question is particularly coined by the observations that unfavorable genotypes associated with psychiatric disorders such as Val-allele of COMT and DRD2/ANKK1 A1-allele are selected in some human ethnic groups." (PMID 26136653, 2015). "Chlorpromazine (CPZ), an FDA- and EMA-approved antipsychotic medication, has been a mainstay of clinical practice in psychiatric disorders for over seven decades, due to its well-characterized ability to antagonize dopamine at the level of the CNS dopamine receptor D2 (DRD2)." (PMID 39026284, 2024). "For this reason, it is possible to assume that the greater relevance of SNPs in DRD2 in response to CAR could be related to the major role played by this receptor in psychiatric disease pathophysiology as well as in the activity of antipsychotic drugs." (PMID 37229261, 2023).
psychiatric disorder (continued). "Genome-wide association studies have implicated the dopamine receptor gene DRD2 in alcohol and tobacco consumption and other psychiatric disorders, although not driven by a frequently studied polymorphism (DRD2/ANKK1 rs1800497)." (PMID 37881572, 2023). "Among them, DRD2 has attracted considerable attention since its agonists can improve the motor symptoms of PD patients without exhibiting the side effects of movement disorders and mental illness." (PMID 34426745, 2021). "Dopamine transporter DAT-1 (SLC6A3) and DRD2 gene for the dopamine-2 receptor are dopaminergic system genes that regulate dopamine reuptake and signaling, and may be part of the pathogenesis of psychiatric disorders including antisocial behaviors and traits." (PMID 28582390, 2017). "In summary, the present study has demonstrated a lack of association between the two genetic variants (BDNF rs6265 and DRD2 rs1799978) and MMT response, contrary to what previously had been believed about the role of these variants in psychiatric disorders and addictive behavior." (PMID 26437921, 2015). "Correlation of RDS and related neurological and psychiatric disorders with DRD2 SNP (a sampling)." (PMID 22408582, 2011). "DAT is regulated by different presynaptic proteins, including DRD2 and DRD3 (acting as sensors of extracellular DA concentration, regulating the synthesis and release of DA), and abnormal DAT function is closely associated with several neurodegenerative diseases and psychiatric disorders." (PMID 36059987, 2022). "These included the MHC region; DRD2, the dopamine D2 receptor involved in mood and emotion; MEF2C, a gene that regulates synaptic function; TCF4, a regulator of prefrontal neuronal excitability and RBFOX1, a gene splicing regulator that has also been implicated in other psychiatric disorders." (PMID 31576797, 2020). "Central among these were cytokine signaling (e.g., IL‐1β, IL‐8) and dopaminergic transmission (DRD2, SLC6A3), underscoring the intricate crosstalk between the immune system and brain function in the pathophysiology of severe mental illness." (PMID 40922454, 2025). "Besides its well-known clinical efficacy in the treatment of psychiatric disorders, several recent reports depict CPZ as a multifaceted drug that is gaining increasing relevance in oncology, being able to interfere, beyond DRD2 at the synaptic level, with several cancer-related cellular factors." (PMID 34740374, 2021). "Lastly, more recent neuroimaging studies showed that the presence of some DRD2 and DRD4 might, respectively, modulate the gyrification and the functional activity of cortical areas involved in cognitive processes that are impaired in ADHD and other psychiatric disorders." (PMID 34658761, 2021).
cancer (81 papers, 1994 to 2026). A tumor composed of atypical neoplastic, often pleomorphic cells that invade other tissues. "There is considerable evidence that DRD2 deficiency causes to endoplasmic reticulum (ER) stress which is required for the control of cancer cell growth." (PMID 35372029, 2022). "TCGA data showed that DRD2 is elevated in several types of human cancer including OC, and the high expression of DRD2 is often associated with a decrease in the risk of OC progression and prognosis." (PMID 35372029, 2022). "Interestingly, epidemiologic studies have shown schizophrenic patients, who inherently have elevated DRD2 signaling, have an increased risk of cancer but that this risk returns to normal with DRD2 antagonists." (PMID 29108308, 2017). "Interestingly, some DRD2 variant genotypes have been associated with a higher affinity to smoking and a lower likelihood of smoking cessation, which has been proposed to be a probable cause behind the familial aggregation of smoking-related cancers." (PMID 36072788, 2022). "Four genes (CDH13, CYB5R2, RARB2 and SPARC) showed the expected significant hypermethylation (p < 0.05) in cancer patients compared with HDs, whereas DRD2 and LINE-1 were hypomethylated (p < 0.05), as anticipated." (PMID 41008642, 2025). "As a result, DRD2 is emerging as a potential therapeutic target, and dopamine receptor agonists are being explored for their ability to promote DRD2 activation in cancer therapy." (PMID 39575419, 2024). "Studies have shown that DRD2 is overexpressed in various types of cancer, including breast, ovarian, cervical, esophageal, and lung cancers." (PMID 37566075, 2023). "According to research, some DRD2 antagonists like penfluridol, pimozide, and fluspirilene have shown significant cancer suppression." (PMID 37566075, 2023). "We noted an increased proliferation of cancer cells treated with dopamine and the opposite effect when DRD2 antagonists were used." (PMID 36428628, 2022). "Among them, DRD1 and DRD2 subtypes are among the most studied in terms of their role in cancer growth and progression." (PMID 36428628, 2022). "ONC201 has recently been shown to induce apoptosis via targeting DRD2 in a wide variety of different cancer types." (PMID 35372029, 2022). "It was shown that DRD2 antagonists such as pimozide or thioridazine inhibit both proliferation and migration of cancer cells, as well as induce apoptosis." (PMID 36428628, 2022). "Actually, DRD2 antagonists were reported to have anticancer efficacy in cell culture and animal models in several cancer types." (PMID 35461314, 2022). "For cancer cells treated with risperidone (DRD2 antagonist) a decrease of up to 20% in cell viability was observed at the highest concentrations." (PMID 36428628, 2022). "Mechanistic analyses have showed that the therapeutic effect of DRD2 signalling in cancer was mediated through the inhibition of the signalling triggered by the vascular endothelial growth factor (VEGF) on endothelial cells." (PMID 36428964, 2022). "This will require further detailed study to better understand the role of DRD2 in AML that will likely inform the significance of DRD2 acquisition in other human cancers identified here." (PMID 33665638, 2021). "ONC201 is a first‐in‐class small molecule selective orally bioavailable dopamine D2‐like receptor (DRD2) antagonist that is in Phase I‐II clinical trials in select cancers and has been well tolerated with minimal toxicity noted in these human trials." (PMID 33932119, 2021). "Pharmacological inhibition of DRD2 with S(-)eticlopride hydrochloride suppressed cell invasion and migration of multiple human cancer cell lines in vitro." (PMID 34919051, 2021). "The role of DRD2 signaling in several malignant tumors has been investigated; however, the results are contradictory." (PMID 34952904, 2021).
cancer (continued). "ONC201, also known as TIC10 is a small molecule inhibitor of Dopamine Receptor D2 (DRD2) recently showing promise as a well‐tolerated anti‐cancer agent in limited Phase I and Phase II clinical studies." (PMID 33932119, 2021). "In conclusion, 5-HTR1B, 5-HTR2B, DRD1, and DRD2 show mRNA overexpression in a broad spectrum of common and rare cancers." (PMID 31478179, 2020). "Several recent publications demonstrated that DRD2-targeting antipsychotics such as thioridazine induce proliferation arrest and apoptosis in diverse cancer cell types including those derived from brain, lung, colon, and breast." (PMID 31822725, 2019). "ONC206, a second-generation imipridone, has been shown to exhibit potent anti-cancer activity through multiple mechanisms, including the antagonism of dopamine receptor D2 (DRD2), CLpP agonism, and TRAIL activation, disrupting mitochondrial protein homeostasis and inducing cellular stress responses." (PMID 40699850, 2025). "ONC201 is a dopamine receptor D2 (DRD2) antagonist and caseinolytic mitochondrial matrix peptidase proteolytic subunit P (ClpP) agonist that induces cancer cell apoptosis, cell cycle arrest, and antiproliferative effects, including effects on solid tumors and hematological malignancies." (PMID 40210723, 2025). "Jude Hospital, to show limited DRD2 expression across pediatric cancers." (PMID 37589388, 2024). "However, paliperidone, a DRD2 antagonist, is reported to inhibit GBM growth and decrease the expression of programmed death-ligand 1(PD-L1) in GBM, suggesting different roles of DRD2 in different types of cancer." (PMID 37215113, 2023). "Additionally, DRD2 is a key component of the dopamine signaling pathway that is involved in normal growth and development, as well as cancer development." (PMID 37566075, 2023). "Additionally, several in vitro and in vivo studies have demonstrated the potential of DRD2 antagonists in other cancer types characterized by DRD2 upregulation including breast, prostatic, pancreatic, blood, oral, lung, gastric, and renal malignancies." (PMID 37601686, 2023). "According to TCGA data, human PPGLs have the highest DRD2 mRNA expression of all cancers." (PMID 37691636, 2023). "DRD2 antagonists could also induce M1-polarization of macrophages and decrease PD-L1 expression in cancer cells via inhibition of ERK and STAT3 signaling pathways." (PMID 36072788, 2022). "Nevertheless, this peptide may serve as a potential useful agent with therapeutic efficacy in cancers expressing DRD2 receptors, for which DRD2 antagonism is crucial to produce antitumor effects." (PMID 36428628, 2022). "Recent evidence showed that dopamine receptor D2 (DRD2)-targeting antipsychotic drugs such as penfluridol exert oncostatic effects on several cancer types, but the effect of penfluridol on RCC remains unknown." (PMID 35461314, 2022). "The DRD2 protein level in fibroblasts was significantly lower compared to cancer cells." (PMID 36428628, 2022). "The studies were found that DRD2 was upregulated in many cancers and could increase IL-6 production." (PMID 35280511, 2022). "Thioridazine can also induce apoptosis as well as both promote and inhibit autophagy, depending on the cancer context, although it is unclear whether these effects are mediated by DRD2 antagonism." (PMID 33922599, 2021). "DRD2 involvement in cancer stem cell maintenance and proliferation was previously reported." (PMID 34422720, 2021). "Furthermore, by applying BANDIT to anti-cancer compounds in clinical development, Dopamine receptor D2 was identified and validated as a target and a compound targeting Dopamine receptor D2 is now undergoing clinical trials for cancer." (PMID 34658859, 2021).